CRP (C-reactive protein)
Diseases named in the same sentence as CRP in open-access papers (continued):
Sharing a sentence is not in itself a finding about the gene and the disease.
infection (continued). "As potential biomarkers for fatal outcome, blood culture (qualitative and quantitative), serum levels of C-reactive protein (CRP), as well as 31 selected cytokines and chemokines were assessed during the first three days of infection." (PMID 23520553, 2013). "In the present study, we exhaustively examined blood culture, CRP and cytokines as biomarkers for presence of severe S. aureus bacteraemia and fatal outcome of infection in mice." (PMID 23520553, 2013). "CRP levels were significantly elevated in infected mice compared to placebo-inoculated mice at both 17 and 48 hours after infection (P < 0.01)." (PMID 23520553, 2013). "At that time, CRP was considered as a marker of infection because the onset of the precipitation reaction observed with the sera of these patients was largest when they were critically ill." (PMID 24286072, 2013). "CRP is the main acute-phase protein during infection, inflammation, and tissue damage, serving as a natural immune molecule and proinflammatory medium that actively participates in its own inflammation process." (PMID 23544040, 2013). "The use of a ratio between CRP and albumin would provide a variable capable of merging the information provided by CRP and albumin into an index that correlated positively with infection, i.e., a higher ratio indicates higher inflammatory status." (PMID 23555017, 2013). "CRP is an acute phase reactant that is increased in inflammation and infection, and has long been used as a biomarker indicating these conditions." (PMID 23383316, 2013). "The CRP expression was higher in the cases showing chronic stress (P ≤ 0.001), being more accentuated in the cases with infection, and followed by the cases with anoxia (P ≤ 0.001)." (PMID 23401697, 2013). "When the infection was effectively controlled, the CRP level was normalized after approximately 3 weeks." (PMID 24381509, 2013). "An important role for CRP activation of complement was shown in S. pneumoniae infection models where CRP activation of complement contributed substantially to protection from lethal infection and clearance of bacteria." (PMID 24167754, 2013). "The initial assays used to measure CRP in the circulation were relatively insensitive and for many years a positive value was used as an indication of inflammation or infection." (PMID 24167754, 2013). "Routinely used biomarkers of bacterial etiology of infection, such as C-reactive protein and procalcitonin, have limited usefulness for evaluation of infections since their expression is enhanced by a number of different conditions." (PMID 23690657, 2013). "The authors reported very low concentrations of CRP despite proven infection and suggested choosing a biomarker other than CRP in these particular patients." (PMID 24286072, 2013). "CRP is an acute-phase protein and its synthesis by the liver is rapidly dysregulated in various conditions, including tissue damage and infection." (PMID 24358275, 2013). "To address this issue, we excluded children with signs of infection or inflammation, as indicated by a high white blood cell count or high C-reactive protein levels." (PMID 24373608, 2013). "CRP, synthesized in the liver, is an acute phase protein that is rapidly identified in the plasma in cases of infection or tissue damage." (PMID 24223640, 2013). "Sixteen infants had elevated CRP levels >0.5 mg/dL and received antibiotic treatment (infection group: Inf)." (PMID 23365583, 2013). "This study demonstrates that circulating hepcidin-25 concentrations are strongly predicted by both infection/inflammation markers (CRP and IL-6) and iron status markers (SF, ZPP and sTfR) in infants in rural sub-Saharan Africa." (PMID 23460869, 2013). "Accordingly, our data suggest the routine use of CRP as a standard infection marker should be reconsidered." (PMID 24349403, 2013). "Marked CRP variability was often presumably due to subclinical fluctuations in inflammation/infection status." (PMID 23579782, 2013).
infection (continued). "Regarding the discriminative power for infection, the IG count was more indicative than other clinical parameters such as CRP, LBP and IL-6, which had a sensitivity of less than 68%." (PMID 23398965, 2013). "Because CRP is a strong acute phase reactant it is widely used as a marker of inflammation and infection." (PMID 24167754, 2013). "Questions remain regarding the predictive value, sensitivity, and specificity of CRP to diagnose infection in ICU patients, especially in patients receiving specific treatments (e.g., glucocorticoids or statins)." (PMID 24286072, 2013). "VAD was defined as RBP concentrations equivalent to plasma retinol <0.7 μmol/L; infection was defined as CRP >5 ml/L." (PMID 23442248, 2013). "CRP is an acute phase protein produced by hepatocytes predominantly in response to inflammation and infection." (PMID 23923051, 2013). "Although all parameters except CRP were significantly increased in infected patients, the highest discriminative power for infection in the first 48 hours was shown by the total number of immature granulocytes (P < 0.0001)." (PMID 23398965, 2013). "For a cut-off of 8.7 mg/dL, the sensitivity and specificity of CRP for a diagnosis of infection were 93.4 and 86.1%, respectively." (PMID 24286072, 2013). "According to AHA recommendations, CRP levels of 10 mg/l or greater represent evidence of active infection, systematic inflammatory processes, or trauma, and thus those individuals were excluded." (PMID 23670530, 2013). "C reactive protein (CRP) is a well-known acute phase reactant protein whose concentration rises in response to inflammation or infection." (PMID 24527683, 2013). "Our results show that CRP shows high specificity in confirming infection and high sensitivity in predicting mortality." (PMID 23869218, 2013). "From peak at Day 0–2 to Day 7, CRP decreased when (bloodstream) infection and septic shock (Day 0–2) resolved and increased when complications such as a new (bloodstream) infection or septic shock (Day 3–7) supervened." (PMID 23762396, 2013). "In light of detecting infection, the other measured inflammatory markers (CRP level, ESR and WBC) have also been thought to be useful." (PMID 23943224, 2013). "Since neurological symptoms are often exacerbated by infection, we initially assessed plasma levels of the inflammatory reactant CRP in plasma from HP and LP groups." (PMID 23671673, 2013). "C-reactive protein, a conserved acute-phase protein synthesized in the liver and involved in inflammation, infection, and tissue damage, is an informative biomarker for human cardiovascular disease." (PMID 26317021, 2013). "C-reactive protein (CRP) is a protein produced mainly from hepatocytes in acute episodes of inflammation or infection." (PMID 23367494, 2013). "In low-grade infection, the values of systemic inflammatory biomarkers, such as C-reactive protein (CRP), are often normal." (PMID 24308006, 2013). "CRP levels were increased in the infected as well as in the non-infected neonates at the time of diagnosis indicating that their levels increase in infection as well as in inflammation." (PMID 23869218, 2013). "IL-6 is the stimulus to CRP production, and CRP is considered a good marker for infection in later stages." (PMID 23401697, 2013). "The ROCs indicated that ADN ratio was a better predictor of postoperative infection than preoperative ADN levels, blood loss, operation time, or CRP levels." (PMID 23520452, 2013). "Serum CRP level is a sensitive marker of inflammation that is elevated in response to tissue damage or infection and has been shown to be a prognostic factor in OSCC." (PMID 23383155, 2013). "The table shows that CRP changes particularly predict changes in the status of infections and their complications knowingly BSI and septic shock, whereas PCT changes primarily predict the latter complications and the course of organ failure." (PMID 23762396, 2013).
infection (continued). "An increase in CRP levels has been described as a crucial indicator for the diagnosis of postoperative complications in surgical patients such as infection, SIRS, sepsis, anastomotic leakage or mesenterial ischemia." (PMID 23409097, 2013). "Another interesting aspect of this study was the time course of CRP in a surgical population with uncontrolled infection." (PMID 24286072, 2013). "Maximum CRP levels > 3 mg/dL had positive predictive values > 20% for proven or probable early-onset infections or inflammation." (PMID 23484158, 2013). "C-reactive protein variations overtime appears to have a good performance for the diagnosis of infection." (PMID 22824162, 2012). "This has a strong pathophysiological basis, as PCT levels are reported to rise within 3 to 4 hours in response to infection as compared with the 24 to 48 hours required for CRP." (PMID 22257704, 2012). "Surgical trauma induces a significant increase in CRP levels, which can reduce its predictive value for the diagnosis of infection in the early postoperative period." (PMID 23275327, 2012). "CRP recognizes additional pathogens, including fungi, yeasts, and bacteria, thus promoting phagocytosis and resistance to infection." (PMID 23316195, 2012). "Elevated CRP levels are seen in infection, in autoimmune disease, in surgery, meconium aspiration and recent vaccination." (PMID 23493845, 2012). "The infected animals had elevated CRP levels throughout the infection period, exhibiting an average of 1.86, 2.00, 2.13, 1.73 and 1.44 times the values of the control animals 5 days, 3 weeks (1A), 3 weeks (mix), 3 months and 6 months, respectively." (PMID 23240022, 2012). "This approach failed to produce meaningful results for the ability of PCT and CRP to identify patients who developed a documented infection, reflecting the inconsistencies and great heterogeneity of the data." (PMID 22257704, 2012). "Procalcitonin is superior to currently available tools, especially CRP, as a biomarker for infection, especially in pleural diseases." (PMID 23251353, 2012). "CRP levels become elevated after infection, and inverse relationships between SES and illness have been noted." (PMID 23049799, 2012). "Several studies have confirmed that serial measurements of CRP are useful in the monitoring of clinical course as well as assessment of patient outcome in different severe infections." (PMID 22449513, 2012). "According to the study’s findings, simultaneous measurement of PCT, IL-6 and hs-CRP is more sensitive in diagnosis of neonate infections." (PMID 22708043, 2012). "With the resolution of infection, the concentration of CRP decreases at a rate that is dependent on its half-life, since this marker exhibits a first-order elimination kinetics." (PMID 22449513, 2012). "Serum C-reactive protein (CRP) was measured in a sub-set of 664 patients (30% of all cases) if clinically indicated (e.g. suspected infection)." (PMID 22914997, 2012). "PCT concentrations increase more rapidly than CRP (within 2–4 hours) in response to systemic inflammation or infection, remain elevated during the inflammatory process and rapidly return to baseline on resolution of the stimulus." (PMID 23272177, 2012). "With regards to the CRP levels, Group B infection showed a lower CRP mean when compared to Group A (11.0 vs 19.0 mg/dL, p<0.05)." (PMID 22591236, 2012). "CRP production increases rapidly up to 1000-fold within 24–48 hours in response to infection, trauma, and tissue infection, and its concentration reduces the same rapidly after resolution of inflammation." (PMID 22933833, 2012). "Recent studies in surgical patients have also shown that after orthopedic, cardiac, and thoracic surgery PCT was better for detecting postoperative infections than CRP." (PMID 23275327, 2012). "At 17 days after discharge, during a routine follow-up, the infection parameters had again risen (C-reactive protein, 194 mg/l; white blood cell count, 29,800 with 4% banded neutrophils)." (PMID 22526279, 2012).
infection (continued). "More recently, PCT has been found to perform better than CRP in diagnosing postoperative infections after orthopedic, cardiac, and thoracic surgery." (PMID 23275327, 2012). "Meanwhile, infection-induced increases in IL-6 production stimulate hepatocytes to synthesize and secrete acute-phase proteins such as CRP." (PMID 22934219, 2012). "CRP is a standardized and widely used serum indicator of acute-phase response in conditions such as acute inflammations, infections, tissue or organ necrosis, and malignancies." (PMID 22857740, 2012). "Our study found that sTREM-1, PCT, and CRP levels indicate infection, while sTREM-1 and PCT levels predict prognosis." (PMID 22809118, 2012). "Among all biomarkers of infection those more frequently studied are C-reactive protein (CRP) and PCT." (PMID 22824162, 2012). "Normal serum concentration is less than 10 mg/l 8–12 hours after infection or trauma; the increase of acute phase protein in liver the CRP is more important in clinical practice." (PMID 22866907, 2012). "This study is the first to examine the impact of CRP testing on clinical decision-making and to evaluate the evidence base for the utility of this test for different infections in children." (PMID 22943554, 2012). "C- reactive protein has a relatively short half-life making it useful in monitoring infection, inflammation and response to treatment." (PMID 23035863, 2012). "Third, we found great variation in the optimal CRP cutoff level among studies, even for the same type of infection." (PMID 22943554, 2012). "Previous studies have demonstrated that the identification of the individual pattern of CRP ratio response to antibiotic therapy appears to be a reflection of the clinical course of infection independently of other possible confounders." (PMID 22449513, 2012). "In different infections and clinical settings, CRP discriminates, early in the clinical course, survivors from non-survivors." (PMID 22449513, 2012). "To compensate for possibly low sensitivity we used additional criteria for the diagnosis infection (C-reactive protein >10 mg/L, clinical signs of infection as fever, and/or detection of bacteria in smears e." (PMID 23034003, 2012). "The only case with proven early-onset sepsis (EOS) was excluded from analysis as infection elevates CRP and PCT, potentially confounding the effects of HCA on inflammatory markers, which was the primary research question." (PMID 23272177, 2012). "PCT added diagnostic value to the currently routine variables (CRP, WBC count) for the identification of infection in patients with fever." (PMID 22874067, 2012). "CRP is increased in infections, inflammatory arthritis, autoimmune disorders, neoplasia, pregnancy, and aging." (PMID 22866907, 2012). "In contrast, patients with consistent CRP ratio decrease (that is, patterns of fast or slow response) usually have an adequate antibiotic therapy, rapid resolution of infection, and good prognosis." (PMID 22449513, 2012). "CRP peaked much later at 24 h, which is in line with the clinical experience in infection and inflammation." (PMID 22496751, 2012). "This is most likely because patients with a very high CRP level suffered from a different infection than DRM." (PMID 23236510, 2012). "Consistent with this, CRP transgenic (Tg) mice are resistant to infection with Streptococcus pneumoniae, displaying longer survival time and lower mortality rate than normal littermates." (PMID 23316195, 2012). "This practice is most likely influenced by the rapidly increasing literature on the utility of CRP levels for different infections in children and neonates." (PMID 22943554, 2012). "CRP and IgG levels were elevated throughout the span of the experiment, and reached maximum levels 3 weeks and 3 months post infection, respectively." (PMID 23240022, 2012).
infection (continued). "Six of the 30 (20%) included infants with 13 samples of breast milk had a neonatal infection (C-reactive protein >10 mg/L, clinical signs of infection and consecutive therapy with antibiotics)." (PMID 23034003, 2012). "In many studies on infants, C- reactive protein (CRP) and IL-6 have been used to diagnose the early onset of infection." (PMID 23035863, 2012). "One prerequisite for the use of CRP as a diagnostic aid after spine surgery in the early detection of postoperative infection is an understanding of the natural CRP response induced by the procedure." (PMID 21657968, 2011). "Erythrocyte sedimentation rate (ESR) was 67 mm/hr (0–12 Nl) and serum C-reactive protein (CRP; high sensitivity) was 57 mg/L (> 10 mg/L consistent with infection or inflammation)." (PMID 21541994, 2011). "Recently, it was discovered that under local infection-inflammation conditions as reflected by pH and calcium levels, the conformations of CRP and L-ficolin change which leads to a strong interaction between them." (PMID 21283780, 2011). "CRP is a primitive acute-phase inflammatory protein that is released in response to acute injury, infection, or other inflammatory stimuli, such as hypersensitivity reactions, inflammatory diseases, allograft rejection, malignancy, necrosis, and trauma." (PMID 22216303, 2011). "CRP is widely accepted as a biochemical marker of systemic inflammation and routinely used as a marker of infection, inflammation or tissue damage in clinical practice." (PMID 21827658, 2011). "To date, as far as we are aware, this is the largest multiple-center study evaluating the course of a biomarker, CRP, over a period of five days that are the crucial days in which to assess an infection response." (PMID 21762483, 2011). "In contrast to CA-MRSA infection, NF patients with HA-MRSA infection had a significantly higher amputation rate, comorbidity, C-reactive protein level, and involvement of lower extremity." (PMID 22040231, 2011). "C-reactive protein (CRP) has been shown to be a valuable marker in the diagnosis of infection and in monitoring its response to antibiotics." (PMID 21762483, 2011). "In this series, CRP levels were utilized to detect early infections in 348 consecutive spinal procedures." (PMID 21427784, 2011). "The prognostic value of PTX3 as evaluated by ROC curve was better than that for CRP during the first days after diagnosis of bacteremic infection." (PMID 21423699, 2011). "As suggested by Thelander and Larsson 1992), a rapid decline in CRP levels after spine surgery will be interrupted by a second rise or persistent elevation if infection occurs." (PMID 21657968, 2011). "Our model analysis confirmed that the enhancement of complement activity under infection-inflammation condition was attributable to the synergistic action of CRP and L-ficolin and supported the existence of the amplification pathways." (PMID 21283780, 2011). "CRP has long been considered to be a distinct and sensitive biomarker of inflammation, tissue damage, and infection." (PMID 21272380, 2011). "Infection by bacteria containing PC will induce the CRP:L-ficolin mediated amplification pathway: PC→CRP:L-ficolin→MASP2→C4→C2→C3." (PMID 21283780, 2011). "La biologie permet de mettre en évidence une hyperleucocytose et une élévation de la CRP témoignant de l'infection et une perturbation du bilan hépatique en cas de complication biliaire." (PMID 22187585, 2011). "Under infection-inflammation conditions where PC-CRP:L-ficolin or GlcNAc-L-ficolin:CRP complex is formed, the amplification pathways are triggered." (PMID 21283780, 2011). "There were 16 (4.6%) infections; the second rise occurred in 12 cases with a steady rise in 4 of CRP." (PMID 21427784, 2011). "The parameters of infection including, fibrinogen (p = 0.03), white blood cell count (p = 0.001) and C-reactive protein (p = 0.0001) were significantly reduced after daptomycin application." (PMID 21929771, 2011).